TNF (tumor necrosis factor)
Diseases named in the same sentence as TNF in open-access papers (continued):
Sharing a sentence is not in itself a finding about the gene and the disease.
mastitis (continued). "The study detected the molecular prevalence of mycoplasmosis in clinical and subclinical mastitis infected lactating cows, phylogenic analysis of detected strain, immunohistochemical detection of inflammatory TNF‐α and identification of udder histological alterations." (PMID 41026010, 2025). "However, when mastitis occurs in dairy cows, TNF-α and IL-1β are rapidly expressed in the early stages of infection and have powerful proinflammatory functions." (PMID 40105325, 2025). "Our results show that quercetin reduces mastitis by regulating the TNF signaling pathway." (PMID 38630770, 2024). "GYS appears to act against mastitis primarily via the TNF and PI3K-Akt signaling pathways." (PMID 38630770, 2024). "Furthermore, studies have shown that certain cytokines, such as interleukin-1 (IL-1), tumor necrosis factor-alpha (TNF-α), and interleukin-6 (IL-6), are significantly elevated in cows with mastitis, reflecting the immune response to udder infection." (PMID 38585704, 2024). "Similarly, serum levels of TNF-α, IL-1β, and IL-6 were significantly higher in mastitis cows than in the control cows (p < 0.01)." (PMID 37175449, 2023). "The milk from animals with mastitis would provide cytokines IL-1, IL-6, and TNF-α." (PMID 37701910, 2023). "In the murine model of mastitis, Z-d14CFR exhibits favorable therapeutic potential by enhancing the clearance of E. coli in the mammary gland, reducing neutrophils infiltration and expression of TNF-α and IL-1β." (PMID 35563007, 2022). "Moreover, the inflammation of the buffalo udder (i.e., clinical and subclinical mastitis) promoted the increase in cytokines (TNF-α, IL-6, IL-1β, and IFN-γ) production, which impaired the reproductive success in this animal." (PMID 36009715, 2022). "The proinflammatory cytokines IL-1β, IL-6, and TNF-α are important in mastitis." (PMID 35624447, 2022). "The expression of the TNF-α gene is positively correlated with the severity of dairy cow mastitis." (PMID 35433915, 2022). "It has also been reported that the concentrations of TNF-α and IL-6 could be downregulated after treatment with a single-dose T4 phage in an E. coli-induced mastitis mouse model." (PMID 35337027, 2022). "For example, EV downregulated the levels of IL-1β, TNF-α, and iNOS via NF-κB and MAPK signaling pathways in the lipopolysaccharide (LPS)-induced mastitis and adjuvant-induced arthritis, suppressing the production of TNF-α, IL-1β, and IL-6 in adjuvant-induced synovial inflammation in rats." (PMID 35795554, 2022). "The results showed that LGR-1 pretreatment had preventive and protective effects on E. coli induced mastitis, and could reduce cytokines levels such as IL-1β and TNF-α." (PMID 34594329, 2021). "TNF-α, an inflammatory cytokine, plays a key role in preventing mastitis and oncogenic processes." (PMID 33435531, 2021). "IL-6, IL-8, and TNF-α are important pro-inflammatory cytokines involved in mastitis." (PMID 35174140, 2021). "Further studies are warranted to evaluate biomarkers in milk samples obtained from mastitic and healthy cows (special focus will be on PCT, NPT and TNF-α) and correlate these biomarker levels with estimated serum levels and the clinical conditions of mastitis in cows before and after treatment." (PMID 34131523, 2021). "During the process of mastitis pathogenesis, the production of pro-inflammatory cytokines is acutely induced to activate immune responses: firstly IL-8 attracts neutrophils, followed by TNF-α, interferon gamma (IFN-γ), and IL-1β induces tissue inflammation." (PMID 34827927, 2021). "When a cow suffers from mastitis, its mammary epithelial cells can synthesize and secrete a large number of proinflammatory factors, mainly including interleukin (IL)-1β, IL-6, IL-8, tumor necrosis factor (TNF)-α and other cytokines." (PMID 32748871, 2020).
mastitis (continued). "Hence, it is suggested that a potential mechanism to block the development of inflammation, by the effective medicines that used for treating mastitis, is inhibiting TNF signaling pathway through reducing the secretion of TNF." (PMID 32754201, 2020). "Our results show that activation of GPR109A could significantly reduce the expression of N-P65, IL-6, IL-1β, and TNF-α in BMECs, thus inhibiting mastitis." (PMID 32397071, 2020). "Previous studies have reported that a large amount of IL-1 and TNF-α in milk and plasma of animals with mastitis might be important events for the inflammatory reactions in mammary glands." (PMID 30832302, 2019). "The mechanism of key CMM combinations studied here in treating mastitis might be that they reduce the secretion of TNF by inhibiting TNF signaling pathway and block the development of inflammation." (PMID 30911319, 2019). "In cattle, the role of TNF-α has been reported also in an acute mastitis." (PMID 29742137, 2018). "Studies have shown that some plant (like cepharanthine and kaempferol) could attenuate LPS-induced mouse mastitis by suppressing the production of TNF-α, IL-6 and IL-1β." (PMID 29904013, 2018). "vB_EcoM-UFV13 used in an animal model for mastitis reduced the total bacterial load by 90%, as well as inducing pro-inflammatory cytokines such as IL-6 and TNF-α, which makes it a potential biological agent capable of controlling acute infections caused by E. coli dairy cows." (PMID 29717158, 2018). "Previous studies had determined that Wnt, PPAR, CAMs, PI3K-Akt, and TNF signaling pathways could regulate mammary gland development, milk fat synthesis, mastitis, BMECs proliferation and apoptosis." (PMID 30103699, 2018). "Besides, the development of TNF-α was in accordance with the previous report that after natural E. coli mastitis it significantly increased in milk and serum." (PMID 28824576, 2017). "In our study, the level of TNF-α was significantly higher (p<0.05) in mice inoculated with the strong biofilm forming S. aureus than the weak biofilm forming strain even at 48 h post-infection indicating an important role for TNF-α in the observed mammary tissue damage in the mouse mastitis model." (PMID 28129375, 2017). "We may infer that increased cytokines of IL-6 and TNF-α secreted by activated fibroblasts within mammary stroma during mastitis could cooperate with epithelial cells, recruit leukocytes to alveoli, and promote inflammation." (PMID 27272504, 2016). "Furthermore, given that tumor necrosis factor-α (TNF-α) and interleukin (IL)-6 are well-known inflammatory mediators during mastitis, their secretion in medium by INFs and NFs were examined using ELISA kits." (PMID 27272504, 2016). "Besides, TNF-α was also proposed as one of the potential DNA markers in the improvement of immunity to mastitis." (PMID 27733800, 2016). "Cell apoptosis analysis by flow cytometry showed that 107 particles/mL heat-killed mastitis strains caused a substantially increased percentage of apoptotic cells, but none of the other stimuli, TNF-α, LPS, or LTA, cause any changes on apoptotic cell numbers." (PMID 27433029, 2016). "As TrxR is an antioxidant enzyme that can scavenge ROS, CP-induced TrxR1 expression may indicate the activation of cellular defense systems against TNF and other mastitis pathogen challenges." (PMID 27433029, 2016). "Statistical analysis of transcript and protein level expression changes indicated that 10 genes, namely TLR4, MyD88, IL-6, and IL-10, were up-regulated, while, CD14, TNF-α, MD-2, IL-β, NF-κB, and IL-12 were significantly down-regulated in mastitis tissue in comparison with normal tissue." (PMID 25706977, 2015). "In LPS-induced mastitis models, TNF is detected in the plasma and milk of early lactating cows." (PMID 26705479, 2015). "This contrasts with the high concentrations of TNF-α found in milk in the course of mastitis caused by Gram-negative bacteria, which are characterized by a marked loss of milk production." (PMID 23696826, 2013).
mastitis (continued). "In order to characterize the expression of genes associated with immune response mechanisms to mastitis, we quantified the relative expression of the IL-2, IL-4, IL-6, IL-8, IL-10, IFN-γ and TNF- α genes in milk cells of healthy cows and cows with clinical mastitis." (PMID 21637453, 2009). "In future studies, the inflammatory factors (TNFα, IL-2, IL-6), the number of S aureus in mammary gland, and the underlying mechanisms need to be detected, which may provide a theoretical basis for CTE application in the treatment of S. aureus mastitis." (PMID 41309393, 2025). "Therefore, the use of IFN-γ and TNF-α in our study might simulate inflammatory conditions during mastitis." (PMID 40564173, 2025). "High levels of SCC are not only directly related to an increased risk of subclinical mastitis but may also suppress the expression of lactation-related genes and proteins, such as STAT5 and LALBA, through inflammatory factors like IL-6 and TNF-α, leading to decreased milk yield." (PMID 40941289, 2025). "Consequently, mastitis is fundamentally driven by pathogen-triggered cascade activation of an innate immune signaling network centered on NF-κ B, TNF, NLR, and CLR pathways, leading to massive expression of pro-inflammatory cytokines, Chemokines, and acute-phase proteins." (PMID 41156687, 2025). "When studying the effectiveness of SMP against mastitis, it was found that SMP supplementation could inhibit the activities of myeloperoxidase (MPO) and N-acetyl-β-D-glucosaminidase (NAGase) and reduce the expression of IL-6, IL-1β and TNF-α inflammatory factors in rats with mastitis." (PMID 36937857, 2023). "Similarly, upon E. coli stimulation, gut microbiota-dysbiostic mice had more apparent mastitis characteristics compared with control mice, including increased myeloperoxidase activity, tumor necrosis factor (TNF)-α, and interleukin (IL)-1β concentrations in the mammary gland tissue." (PMID 35479637, 2022). "Luteolin inhibited the expression of TNF-α, IL-1β, and IL-6; suppressed IκBα and NF-κB p65 phosphorylation levels; and downregulated the expression of MMP-2 and MMP-9 in S. aureus-induced mastitis, showing its potential in reducing tissue damage and inflammation caused by S. aureus-induced mastitis." (PMID 36111166, 2022). "The lack of disparity in TNFα concentrations with FM treatment or between infection outcome groups recorded in our study may be due to the timing of sampling, as the duration of the elevated TNFα concentrations differ greatly among varying experimental designs of induced mastitis." (PMID 34073753, 2021). "Based on significantly increased TLR4, IκB, TNF-α, IL-1β protein expressions, and NF-κB nuclear protein expression induced by E. coli, we inferred that it activated TLR4/NF-κB signaling pathways in bMECs and macrophages, consistent with E. coli causing mastitis through the TLR4/NF-κB pathway." (PMID 32733409, 2020). "High levels of TNF have been detected in milk from mothers with mastitis; however, this was accompanied by elevated levels of sTNF-RII and IL-1RA, which might protect nursing infants from high pro-inflammatory cytokine levels in the context of such breast infections." (PMID 30723472, 2019). "When analyzing the number of mastitis cases with a lactation-averaged model (model 1 and 2), the gene effects were found to be statistically non-significant, whereas when analyzing the interactions between the TNF-α gene and parity (model 3), significant effects were observed." (PMID 23758855, 2013). "Levels of IFN-γ, IL-4, TNF-α, MYD88, CCL5, TLR4, TLR9, LTF, PRLR, Keap1 and OXSR1 genes expression were significantly up-regulated in ewes affected with mastitis than resistant ones." (PMID 40542007, 2025). "The HC group exhibited disrupted ruminal microbiota, elevated serum levels of LPS, TNF-α, and IL-1β, and a markedly increased milk somatic cell count (SCC) exceeding 500,000/mL, indicating mastitis." (PMID 41362615, 2025).
mastitis (continued). "In the milk of subclinical mastitis in this study, WC1+ γδ T cells exhibited significant upregulation of IFN-γ, IL-2, TNF-α, IL-17, and GZMB." (PMID 41142813, 2025). "However, when mice developed mastitis caused by Coagulase-negative staphylococci (CNS; Staphylococcus aureus, S. chromogenes, S. fleurettii), the inoculated S. aureus produced IL-6 and IL-1β but not TNF-α." (PMID 41148692, 2025). "In the course of mastitis, buffaloes increase the expression of immune genes related to the activation of pathogen recognition (TRL-2, TRL-4) and to the cytokine network (TNF-α, IL-1β, and IL-8), leading to the secretion of pro-inflammatory cytokines." (PMID 39858163, 2025). "Specifically, in subclinical mastitis milk, the expression levels of five cytokines—IFN-γ, IL-2, TNF-α, IL-17, and GZMB—were significantly higher in WC1+ γδ T cells compared to healthy cows." (PMID 41142813, 2025). "Consistent with the lactation insufficiency observed in mastitis, we found that IFN-γ and TNF-α inhibit prolactin-induced STAT5 tyrosine phosphorylation and β-casein expression." (PMID 40564173, 2025). "Mastitis-affected ewes had considerably higher levels of IFN-γ, IL-4, TNF-α, MYD88, CCL5, TLR4, TLR9, LTF, and PRLR gene expression than resistant ones." (PMID 40542007, 2025). "Our molecular docking analysis revealed that TNF and IL-6 were primary targets for interaction with the active GYS constituents, quercetin, and luteolin, against mastitis." (PMID 38630770, 2024). "The levels of IL-1β, IL-6, TNF-α, COX-2, and iNOS in the serum of cows with clinical mastitis were significantly higher than those in the healthy cows (p < 0.001)." (PMID 36875515, 2023). "As expected, a significant increase in the concentrations of proinflammatory cytokines, including TNF, IL6, and IL1β, in the serum and mammary glands of clinical mastitis cases has been observed in several previous studies." (PMID 37620551, 2023). "The levels of these inflammatory factors (L-1β, IL -6, TNF-α, COX-2, and iNOS) in blood decreased after injecting the antibiotics and geraniol into the breast of the dairy cows with clinical mastitis." (PMID 36875515, 2023). "In terms of hub-hub genes, we identified several crucial immune and inflammatory response genes, including TLR2, TLR474, TNF, IL1β, IL1A, IL675, JAK276,77, and IL1068, which play important roles in the pathogen-host interactions during mastitis." (PMID 37620551, 2023). "Tumor necrosis factor (TNF-), a cytokine produced in mastitis and released into the bloodstream, gets to the oviduct and causes the production of prostaglandin F2α." (PMID 38260189, 2023). "In concrete, it has been shown that the production of TNF-α and IL-1β and the phosphorylation of p65 NF-kB are reduced by DMI treatment in a mouse model of mastitis." (PMID 36555614, 2022). "Propionate decreased the inflammatory factors (IL-1β, IL-6, and TNF-α) via inhibiting NF-κB and HDAC in in-vitro and in-vivo mastitis models." (PMID 36145063, 2022). "When cows are infected with mastitis, FEZL, as a transcription factor, is able to induce tumour necrotic factor-α (TNF-α) and interleukin-8 (IL-8) through enhancing SEMA5A." (PMID 35737346, 2022). "Hierarchical level two showed that 18 signaling pathways are involved in the regulation of mastitis, including MAPK, Ras, cGMP-PKG, NF-κb, phosphatidylinositol, and mTOR, wnt, and TNF pathways." (PMID 36204322, 2022). "In serum and whey taken from naturally occurring mastitis-affected animals, significantly higher concentrations of IFN-γ and TNF-α were found." (PMID 35335696, 2022). "LEO attenuated inflammatory responses, which was supported by decreasing TNF-α and IL-1β production in LPS-treated microglia, inhibiting COX-2 mRNA and protein expression in LPS-induced mouse mastitis." (PMID 35883829, 2022).
mastitis (continued). "Kaempferol can reduce the expression of IL-6 and TNF-α and ANGPTL2 in cells, prevent the occurrence of mastitis in mice, inhibit the phosphorylation of NF-κB P65 subunit and the degradation of IκBα, and play a therapeutic role in mastitis." (PMID 35757473, 2022). "Altogether with other selected cytokines, TNF-α and IFN-γ multifunctionality in bovine subclinical and clinical mastitis must be studied." (PMID 35335696, 2022). "MECs can synthesize and secrete inflammatory chemokines and pro-inflammatory cytokines such as interleukin-1 beta (IL-1β), interleukin-6 (IL-6), interleukin-8 (IL-8), and tumor necrosis factor (TNF-α), which are crucial for the occurrence of mastitis." (PMID 35681915, 2022). "They found higher serum levels of IL-1β and IL-2, TNF-α, IL-6, and IFN-γ in subclinical mastitis compared to control cows." (PMID 34484387, 2021). "Previously published research indicated that mastitis involves the NOD-like receptor, IL-17, and TNF signaling pathways." (PMID 34691146, 2021). "We found that gut dysbiotic mice had obvious mastitis features, including increased acinus damage, histological score, MPO activity and pro-inflammatory tumor necrosis factor (TNF)-α and IL-1β expression compared with the control mice." (PMID 34297785, 2021). "The RT-qPCR technique detected the mRNA expressions levels of TNF-α, IL-6, and IL-1β to evaluate the effects of L. plantarum KLDS 1.0344 on LPS-induced mastitis using isolated bMEC." (PMID 34858427, 2021). "In these candidate DEGs of E. coli mastitis, 27 KEGG pathways were found to be enriched with P < 0.05 as the cutoff point, such as the TNF signaling pathway, chemokine signaling pathway, and cytokine–cytokine receptor interaction." (PMID 31921295, 2019). "The inflammatory responses of mastitis at least increase SCC and levels of inflammatory cytokines, including TNF-α, IL-6, and IL-8, in milk." (PMID 31019541, 2019). "TNFAIP6 is upregulated in response to many proinflammatory cytokines such as TNF-α and interleukin-1, and elevated levels of TNFAIP6 have been reported in the plasma of both LPS stimulation and S. aureus-induced mastitis." (PMID 31093495, 2019). "The mastitis indicators including clots, lactate dehydrogenase (LDH), TNF-α, IL-6, IL-8, and total viable count of bacteria (TVC) in milk were examined before and after the YXT treatment to evaluate its effectiveness." (PMID 31019541, 2019). "The observed reduction in mastitis symptoms and improvement of resistance to infection consecutive to immunization is likely to be related to the induction of IFN-γ and reduction in TNF-α production." (PMID 28611405, 2017). "IL-1β, IL-6, and TNF-α expression significantly increased after LPS stimulation both in MMEC and in the mouse mastitis model." (PMID 28255203, 2017). "TLR2, NOD2, and inflammatory cytokines (TNF-α, IL-1β, IL-6, CXCL1, IL-10, TGF-β1, and IFN-γ) are involved in the response to mastitis induced by S. aureus." (PMID 25990971, 2015). "We proposed tumor necrosis factor α (TNF-α), lactoferrin (LTF) and macrophage-expressed lysozyme (mLYZ) genes as potential DNA markers in the improvement of immunity to mastitis." (PMID 23758855, 2013). "Due to their biological functions, TNF-α, LTF and mLYZ genes have been proposed as potential DNA markers for immunity to mastitis." (PMID 23758855, 2013). "Cows with mastitis had higher concentrations of PGF2α in their milk than cows that did not have mastitis Increased prostaglandin production by blastocysts in response to inflammatory cytokines such as TNFα may explain the decreased fertility that is commonly observed after diseases such as mastitis." (PMID 22958469, 2012). "Studies have shown that PS can effectively alleviate Staphylococcus aureus-induced mastitis by inhibiting the activation of pro-inflammatory signaling pathways such as NF-κB/NLRP3, reducing the release of inflammatory factors such as IL-1β and TNF-α." (PMID 41596521, 2026).